SESN3 (sestrin 3)
Description:
May function as an intracellular leucine sensor that negatively regulates the TORC1 signaling pathway. May also regulate the insulin-receptor signaling pathway through activation of TORC2 (By similarity). This metabolic regulator may also play a role in protection against oxidative and genotoxic stresses (By similarity). May prevent the accumulation of reactive oxygen species (ROS) through the alkylhydroperoxide reductase activity born by the N-terminal domain of the protein (By similarity).
Synonyms: SEST3; MGC29667
Tractability: PROTAC: ubiquitination databases record sites on it; its protein half-life has been measured.
Gene: Protein-coding gene on chromosome 11 (95,165,513 to 95,232,541, reverse strand). Ensembl gene ENSG00000149212.
Subcellular location: Cytoplasm
Subcellular location (Human Protein Atlas): Nucleoplasm; Cytosol
Gene Ontology:
Molecular function: protein binding; L-leucine binding; oxidoreductase activity, acting on peroxide as acceptor
Biological process: cellular response to amino acid starvation; cellular response to glucose starvation; negative regulation of TORC1 signaling; cellular response to L-leucine; cellular response to leucine starvation; positive regulation of macroautophagy; cellular response to amino acid stimulus; glucose homeostasis; regulation of insulin receptor signaling pathway; regulation of response to reactive oxygen species; response to insulin; TORC2 signaling
Cellular component: cytoplasm; GATOR2 complex; nucleus; TORC2 complex
Genetic constraint (gnomAD): Loss-of-function variants: 7 observed, 30.95 expected, observed/expected ratio (o/e) 0.23, 90% interval 0.13 to 0.43. The upper end of that interval is the gene's LOEUF score, 0.43, which puts it in group 1 of 6, group 1 being the genes least tolerant of losing a copy. Missense variants: 298 observed, 464.96 expected, observed/expected ratio (o/e) 0.64, 90% interval 0.58 to 0.7. Synonymous variants: 137 observed, 160.85 expected, observed/expected ratio (o/e) 0.85, 90% interval 0.74 to 0.98.
Homologues: Orthologues: chimpanzee SESN3 (99% identical), macaque SESN3 (99% identical), rabbit SESN3 (99% identical), dog SESN3 (98% identical), pig SESN3 (98% identical), rat Sesn3 (95% identical), mouse Sesn3 (94% identical), guinea pig SESN3 (82% identical), tropical clawed frog sesn3 (79% identical), zebrafish sesn3 (64% identical), Drosophila melanogaster Sesn (43% identical), Caenorhabditis elegans sesn-1 (26% identical). Paralogues in human: SESN1 (61% identical), SESN2 (54% identical).
Diseases named in the same sentence as SESN3 in open-access papers:
SESN3 is named in the same sentence as 54 diseases in open-access papers, as found by Europe PMC text mining. Sharing a sentence is not in itself a finding about the gene and the disease. The quoted sentences say what the papers report.
Insulin resistance (6 papers, 2015 to 2025). Increased resistance towards insulin, that is, diminished effectiveness of insulin in reducing blood glucose levels. "Transcriptome results identified many DEGs linked to insulin resistance, fatty acid β oxidation, and inflammation, including IGF2BP2, LEPR, RAP1A, SESTRIN 3, and ITLN1 that have also been reported in human T2DM." (PMID 40878918, 2025). "It is shown that Sesn3 liver-specific knockout (KO) mice exhibit insulin resistance and glucose intolerance, and Sesn3 transgenic mice were protected against insulin resistance induced by a high fat diet (HFD)." (PMID 33425907, 2020). "Previous experiments in liver-specific Sesn3 transgenic mice and knockout mice showed that the transgenic mice were protected against insulin resistance induced by a high-fat diet, while the Sesn3 knockout mice showed metabolic defects such as insulin resistance and glucose intolerance." (PMID 34803916, 2021). "Therefore, deletion of Sestrin 3 in the liver results in insulin resistance and glucose intolerance and Sestrin 3 transgenic mice are protected against insulin resistance induced by a high-fat diet." (PMID 30011848, 2018). "The genes adiponectin receptor 1, sestrin 3, KCNJ15 and G-protein coupled receptor 27 have all been described to play a role in insulin resistance, decreased insulin secretion and impaired blood glucose homeostasis." (PMID 25768297, 2015). "Sesn2 ablation exacerbates obesity-induced mTORC1-S6K activation, and moreover, the concomitant ablation of Sesn2 and Sesn3 provokes hepatic mTORC1-S6K activation and insulin resistance even in the absence of nutritional overload and obesity." (PMID 33425907, 2020).
lung carcinoma (4 papers, 2019 to 2022). "In previous studies, the down-regulation of SESN2 was shown to accelerate both colitis and colon carcinogenesis, while SESN1 and SESN3 were found to be strongly down-regulated in various types of cancer tissues, such as lung cancers and lymphomas." (PMID 35195231, 2022). "For lung cancer, we ensure that C4BPA, SESN3, and IRS1 are highly expressed in some specific groups." (PMID 33133130, 2020). "For lung cancer, we select five essential genes, such as PYGB, C4BPA, SESN3, MMP10, IRS1." (PMID 33133130, 2020).
liver cancer (3 papers, 2021 to 2025). An epithelial or non-epithelial malignant neoplasm that arises from the liver. "Here, CREB1 enhanced SESN3 expression by binding to SESN3 promoter and subsequently boosted the antioxidant capacity of liver cancer cells." (PMID 39863613, 2025). "To confirm sorafenib resistance of mTOR-activated liver cancer cells relying on high expression of SESN3, we overexpressed SESN3 in SNU886/shmTOR cells." (PMID 39863613, 2025). "In contrast, a later study indicated that increased expression of Sesn3, another member of the Sestrin family, correlates with improved survival rates in animal models of liver cancer." (PMID 40361504, 2025). "In our study, pifithrin-μ inhibited HSP70 to reduce the transcriptional activity of CREB1 and the expression of SESN3, consequently suppressing liver cancer cell proliferation and tumorigenesis." (PMID 39863613, 2025). "Next, we sought to determine whether SESN3 was involved in the regulation of sorafenib resistance in mTOR-activated liver cancer cells." (PMID 39863613, 2025). "However, a study examining the activity of Sesn3 in liver cancer investigated its impact on cancer stemness." (PMID 40361504, 2025).
autoimmune disease (2 papers, 2025). A disorder resulting from loss of function or tissue destruction of an organ or multiple organs, arising from humoral or cellular immune responses of the individual to their own tissue constituents. "Another breakthrough from our study is the identification of the potential mechanism by which the RA locus rs4409785 affects the expression of SESN3, a gene that plays a pivotal role in a specific subset of T cells implicated in the pathogenesis of autoimmune diseases." (PMID 39930543, 2025). "SESN3 and CLNK were both associated multiple autoimmune diseases." (PMID 41299435, 2025). "A recent study suggests that SESN3+ memory T cells, a subset not extensively studied before, may play a significant role in the development of arthritis or autoimmune diseases." (PMID 39930543, 2025).
colitis (2 papers, 2016 to 2022). Inflammation of the colon. "Sesn2-/-/Sesn3-/- mice also showed a dramatic decrease in colon length when compared to WT mice, indicative of strongly exacerbated DSS-induced colitis." (PMID 26913956, 2016).
diabetes (2 papers, 2020 to 2021). "Therefore, it is conceivable that SESN3 is associated with the seizures following ischemia in diabetes." (PMID 33519354, 2020). "In the skeletal muscle of mice and the leg muscle biopsies of human diabetics, Sesn3 was increased, which would offer parts of explanation for the adipogenic phenotype we observed." (PMID 34946801, 2021). "The present study aimed to reveal the involvement of SESN3 in seizures following transient cerebral ischemia in diabetes." (PMID 33519354, 2020). "In order to reveal whether SESN3 is related to post-ischemia seizures or diabetes, we detected the expression of SESN3 in each group of animals." (PMID 33519354, 2020). "However, the role of SESN3 in diabetes after stress, such post-ischemia seizures, remains unclear." (PMID 33519354, 2020).
endometrial cancer (2 papers, 2019 to 2024). Primary or metastatic malignant neoplasm involving the endometrium (mucous membrane that lines the endometrial cavity). "The other two members of Sestrin family, SESN2 and SESN3 have been reported to be involved in anoikis resistance in endometrial cancer cell lines." (PMID 38516781, 2024). "Moreover, SESN2 and SESN3 have been reported involved in anoikis resistance of endometrial cancer cell lines, which are regulated by miRNAs." (PMID 38516781, 2024). "Taken together, these preliminary experiments could warrant further studies into the role of SESN3 in the endometrial cancer anoikis mechanism." (PMID 31073887, 2019).
ischemia (2 papers, 2020 to 2025). A hypoperfusion of the BLOOD through an organ or tissue caused by a PATHOLOGIC CONSTRICTION or obstruction of its BLOOD VESSELS, or an absence of BLOOD CIRCULATION. "Quantitative PCR data indicated that SESN3 mRNA expression was 43.8% higher in diabetic animals after ischemia than that of the controls (STZ-ischemia: 143.8 ± 6.0% of control, P < 0.05)." (PMID 33519354, 2020). "Our results showed that SESN3 up-regulation played an important role in hippocampal hyperexcitability and contributed to post-ischemia epileptogenesis in diabetic animals, through down-regulation of Kv4.2-mediated IA currents." (PMID 33519354, 2020). "To investigate the role of SESN3 in post-ischemia seizures under diabetic condition, we established a mouse model of post-ischemia seizures." (PMID 33519354, 2020). "Compared with the control (100 ± 8.4%), there were no significant changes in the expression of SESN3 protein in the ischemia group (110.7 ± 4.7%), or diabetic group, both P > 0.05." (PMID 33519354, 2020).
non-alcoholic steatohepatitis (2 papers, 2021 to 2022). "Moreover, SESN3 has been demonstrated to protect against diet-induced non-alcoholic steatohepatitis (NASH) in mice by directly inhibiting SMAD3 through protein–protein interaction, thus suppressing the TGFβ-SMAD3 signal pathway." (PMID 34946801, 2021). "By suppressing the SMADs family, SESN3 has been shown to be involved in TGF-Smads signaling and to protect mice from diet-induced non-alcoholic steatohepatitis." (PMID 35954183, 2022). "Besides, SESN3 has been demonstrated to be in involved TGFβ-Smads signaling by inhibiting the SMADs family at both protein and mRNA expression levels, thus protecting against diet-induced non-alcoholic steatohepatitis (NASH) in mice." (PMID 34946801, 2021).
non-small cell lung carcinoma (2 papers, 2019 to 2020). A group of at least three distinct histological types of lung cancer, including non-small cell squamous cell carcinoma, adenocarcinoma, and large cell carcinoma. "Sesn3 induces apoptosis of human non-small cell lung cancer (NSCLC) cells in dietary compound cucurbitacin B treatment." (PMID 33425907, 2020).
ovarian carcinoma (2 papers, 2017 to 2019). A malignant neoplasm originating from the surface ovarian epithelium. "Taken together, our data highlights the crucial effects of SESN2 and SESN3 on NK-92 cell-mediated anti-ovarian cancer activity." (PMID 29163816, 2017). "The up-regulation of SESN2 and SESN3 in intratumoral NK-92 cells was also observed in another subcutaneous ovarian cancer model using SKOV3 cells." (PMID 29163816, 2017). "In this study, using an ovarian cancer xenograft mouse model and NK-92 cell line, we identified the up-regulation of SESN2 and SESN3 in intratumoral NK-92 cells." (PMID 29163816, 2017). "SESN2 and SESN3 suppress NK-92 cell-mediated cytotoxic activity on ovarian cancer cells through the induction of AMPK and inhibition of mTORC1, pointing at its potential relevance for immunotherapy in ovarian cancer." (PMID 31205582, 2019). "In conclusion, our data highlights the negative effects of SESN2 and SESN3 on NK-92 cell-mediated anti-ovarian cancer activity." (PMID 29163816, 2017).
prostate carcinoma (2 papers, 2017 to 2019). A carcinoma that arises from epithelial cells of the prostate gland. "A study conducted in patients affected by prostate cancer reported that downregulation of SESN3 gene was associated with fatigue intensification during EBRT." (PMID 31546746, 2019).
psoriasis (2 papers, 2020 to 2021). An autoimmune condition characterized by red, well-delineated plaques with silvery scales that are usually on the extensor surfaces and scalp. "Over-representation of Tregs, dysfunctional NR4A1-expressing T cells, and senescent SESN3+ T cells were detected in psoriasis." (PMID 34777377, 2021). "We also observed an expansion of regulatory T cells in three of five patients with psoriasis, and an additional population of T cells characterized by expression of SESN3, a marker of T cell senescence, SATB1, and FURIN." (PMID 33053333, 2020).
rheumatoid arthritis (2 papers, 2025). A chronic, systemic autoimmune disorder characterized by inflammation in the synovial membranes and articular surfaces. "We uncover BCL2L11 as the probable causal gene within the rheumatoid arthritis (RA) locus rs13396472, despite the GWAS variants’ intronic positioning relative to ACOXL, and we identify mechanisms involving SESN3 dysregulation in the RA locus rs4409785." (PMID 39930543, 2025). "An analysis using human T cells found that the signal for rheumatoid arthritis (the same signal as one for T1D) in the SESN3 region is driven by chromatin interactions that regulate SESN3 expression." (PMID 41299435, 2025).
Stroke (2 papers, 2020 to 2023). Sudden impairment of blood flow to a part of the brain due to occlusion or rupture of an artery to the brain. "Studies conducted in diabetic animal models have indicated that the upregulation of sestrins in the hippocampus and SESN3 are associated with seizures after stroke in diabetic animals." (PMID 37059430, 2023). "The significant downregulation of Sesn3 observed on our analysis suggests a potential loss of protection against muscle catabolism, possibly contributing to stroke-induced muscle atrophy." (PMID 32629989, 2020).
type 2 diabetes (2 papers, 2017 to 2021). "Moreover, it has been shown that only Sestrin 3 (Sesn 3) was upregulated in vastus lateralis of type 2 diabetes patients compared to healthy individuals but its role is more likely to be linked to skeletal muscle differentiation than regulating glucose and lipid metabolism." (PMID 28529490, 2017). "In type II diabetes, the expression of SESN3, which affects skeletal muscle differentiation without changing glycolipid metabolism, was increased." (PMID 33932987, 2021).
atherosclerosis (1 paper, 2026). A disease characterized by the build-up of fatty material and calcium deposition in the arterial wall resulting in partial or complete occlusion of the arterial lumen. "The clinical evidences support the potential role of FOXP1 and SESN3 as protective factors against atherosclerosis." (PMID 41355963, 2026). "Notably, our work highlights the potential of SESN3-targeted agents as novel intervention method for atherosclerosis, thereby offering a promising therapeutic strategy to inhibit atherosclerotic progression by delaying endothelial cell senescence." (PMID 41355963, 2026). "Moreover, the expression of FOXP1 was positively correlated with SESN3 and negatively correlated with CDKN2A, MMP9, and ICAM1 in human atherosclerosis plaques." (PMID 41355963, 2026).
breast carcinoma (1 paper, 2025). "Then, we developed a risk prognostic model based on expression levels of PIK3CA, SESN3, ANXA5, MYD88, DPP4, DAXX, and CRIP1 to predict clinical outcomes in patients with breast cancer." (PMID 41357233, 2025). "Our research reveals a novel role for the SESN3 gene in influencing breast cancer progression via m6A or PCD, which paves the way for in-depth future studies." (PMID 41357233, 2025). "Moreover, the expression levels of SESN3, CRIP1, DPP4 and PIK3CA were significantly upregulated in breast cancer samples compared to control samples." (PMID 41357233, 2025).
colon cancer (1 paper, 2023). "The authors clearly demonstrated that colon cancer HCT116 and HT29 cell lines treated with 5-FU expressed a higher level of SESN2 and increased transcripts of SESN1, but not of SESN3 protein." (PMID 37284849, 2023).
coronary artery diseases (1 paper, 2020). "In a previous study, circulating Sesn1, Sesn2, and Sesn3 were reported to be increased in patients with coronary artery diseases, while the amplitude of the increase in Sesn levels was closely related to the degree of stenosis and oxidative stress in CAD patients." (PMID 32626541, 2020).
esophageal squamous cell carcinoma (1 paper, 2022). Esophageal squamous cell carcinoma (ESCC) is a type of esophageal carcinoma (EC) that can affect any part of the esophagus, but is usually located in the upper or middle third. "SESN3, which is an encoding member of the sestrin family of stress-induced proteins, served as an oncogene in esophageal squamous cell carcinoma cells." (PMID 36400759, 2022).
hearing loss (1 paper, 2023). "Normothermia TTM upregulated 13 genes associated with hearing loss, including Loxhd1, Tecta, Zmiz1, Espn, Gjb2, Sesn3, Bdp1, Hg, Pax3, Rnls, Syne4, P2rx2, and Pou3f4." (PMID 38298897, 2023).
Hypertension (1 paper, 2020). The presence of chronic increased pressure in the systemic arterial system. "In conclusion, we found that plasma Sesn1, Sesn2, and Sesn3 levels were increased in hypertension patients and positively correlated to the blood pressure values." (PMID 32626541, 2020). "Nondipper hypertension patients exhibited higher plasma Sesn1, Sesn2, and Sesn3 levels when compared to dipper hypertension patients." (PMID 32626541, 2020). "In the present study, the plasma levels of the antioxidant proteins Sesn1, Sesn2, and Sesn3 in hypertension patients were detected." (PMID 32626541, 2020). "The results of our study revealed that Sesn1, Sesn2, and Sesn3 levels were significantly increased in hypertension patients when compared with the normotensive subjects." (PMID 32626541, 2020). "This study is aimed at investigating the level of circulating Sesn1, Sesn2, and Sesn3 in hypertension patients." (PMID 32626541, 2020). "Therefore, this study is aimed at examining plasma Sesn1, Sesn2, and Sesn3 levels in hypertension patients." (PMID 32626541, 2020). "Compared with the normotensive subjects, Sesn1, Sesn2, and Sesn3 levels were increased in patients with hypertension, with a gradual increase between the groups with grade I, grade II, and grade III hypertension." (PMID 32626541, 2020). "Furthermore, plasma Sesn1, Sesn2, and Sesn3 levels were positively correlated to both SBP and DBP in hypertension patients." (PMID 32626541, 2020). "Moreover, Sesn1, Sesn2, and Sesn3 levels were elevated in patients with dipper hypertension and further increased in patients with nondipper hypertension." (PMID 32626541, 2020).
melanoma (1 paper, 2025). A malignant, usually aggressive tumor composed of atypical, neoplastic melanocytes. "Upregulation of Sestrin 2- but not Sestrin 3- by MCL1 depletion was observed in a panel of melanoma cell lines, arguing for the generalization of this effect in melanoma cells." (PMID 41326406, 2025).
myocardial infarction (1 paper, 2025). Gross necrosis of the myocardium, as a result of interruption of the blood supply to the area, as in coronary thrombosis. "Taken together, these findings suggest that therapeutic approaches targeting the miR-25/SESN3 axis would be most beneficial as a preventive measure in high-risk patients or as an immediate intervention following myocardial infarction." (PMID 39857395, 2025).